PLA2G5 (phospholipase A2 group V)
Description:
Secretory calcium-dependent phospholipase A2 that primarily targets extracellular phospholipids. Hydrolyzes the ester bond of the fatty acyl group attached at sn-2 position of phospholipids (phospholipase A2 activity), preferentially releasing fatty acyl groups with a low degree of unsaturation such as oleoyl (C18:1) and linoleoyl (C18:2) groups. Hydrolyzes low-density lipoprotein (LDL) phospholipids releasing unsaturated fatty acids that drive macrophage polarization toward an M2 phenotype (By similarity). May act in an autocrine and paracrine manner. Contributes to lipid remodeling of cellular membranes at different subcellular locations and generation of lipid mediators involved in pathogen clearance. Cleaves sn-2 fatty acyl chains of cardiolipin, a major component of the inner membrane of mitochondria and bacterial membranes. Promotes phagocytosis of bacteria in macrophages through production of lysophosphatidylethanolamines. Displays bactericidal activity against Gram-positive bacteria by directly hydrolyzing phospholipids of the bacterial membrane. Promotes phagocytosis and killing of ingested fungi likely through controlling phagosome-lysosome fusion and phagosome maturation (By similarity). Plays a role in biosynthesis of cysteinyl leukotrienes (CysLTs) in myeloid cells. In eosinophils, triggers perinuclear arachidonate release and LTC4 synthesis in a PLA2G4A-independent way. In neutrophils, amplifies CysLTs biosynthesis initiated by PLA2G4A. Promotes immune complex clearance in macrophages via stimulating synthesis of CysLTs, which act through CYSLTR1 to trigger phagocytosis (By similarity). May regulate antigen processing in antigen-presenting cells (By similarity). In pulmonary macrophages regulates IL33 production required for activation of group 2 innate lymphoid cells (By similarity). May play a role in the biosynthesis of N-acyl ethanolamines that regulate energy metabolism. Hydrolyzes N-acyl phosphatidylethanolamines to N-acyl lysophosphatidylethanolamines, which are further cleaved by a lysophospholipase D to release N-acyl ethanolamines.
Synonyms: FRFB; GV-PLA2; PLA2-10; hVPLA(2)
Tractability: Small molecule: a drug acting on it is in phase 2 or 3 trials; a high-quality ligand is known; it belongs to a druggable protein family. Antibody: UniProt places it where antibodies can reach, with high confidence; its Gene Ontology location is reachable by antibodies, with high confidence; UniProt predicts a signal peptide or a membrane-spanning region. PROTAC: a small molecule that binds it is known.
Target class: Enzyme; Hydrolase
Chemical probes: BAY-439 (high quality)
Gene: Protein-coding gene on chromosome 1 (20,028,179 to 20,091,911, forward strand). Ensembl gene ENSG00000127472.
Subcellular location: Secreted; Cell membrane; Cytoplasmic vesicle, phagosome; Recycling endosome; Golgi apparatus, cis-Golgi network; Golgi apparatus, trans-Golgi network
Pathways (Reactome):
Metabolism: Acyl chain remodelling of PC; Acyl chain remodelling of PE; Acyl chain remodelling of PG; Acyl chain remodelling of PI; Acyl chain remodelling of PS; Synthesis of PA
Gene Ontology:
Molecular function: phospholipase A2 activity; calcium ion binding; phospholipid binding
Biological process: leukotriene biosynthetic process; phosphatidylcholine catabolic process; positive regulation of ERK1 and ERK2 cascade; positive regulation of immune complex clearance by monocytes and macrophages; positive regulation of phospholipase activity; low-density lipoprotein particle remodeling; negative regulation of T cell proliferation; phagosome-lysosome fusion; phosphatidylcholine metabolic process; phosphatidylglycerol metabolic process; phospholipid metabolic process; positive regulation of antifungal innate immune response; positive regulation of macrophage derived foam cell differentiation; positive regulation of opsonization; positive regulation of phagocytosis; positive regulation of phagosome maturation; arachidonate secretion; lipid catabolic process
Cellular component: early phagosome; extracellular region; phagolysosome; plasma membrane; recycling endosome; Golgi apparatus; phagocytic vesicle
Genetic constraint (gnomAD): Loss-of-function variants: 10 observed, 16.05 expected, observed/expected ratio (o/e) 0.62, 90% interval 0.38 to 1.06. The upper end of that interval is the gene's LOEUF score, 1.06, which puts it in group 4 of 6, group 1 being the genes least tolerant of losing a copy. Missense variants: 158 observed, 169.94 expected, observed/expected ratio (o/e) 0.93, 90% interval 0.82 to 1.06. Synonymous variants: 65 observed, 70.07 expected, observed/expected ratio (o/e) 0.93, 90% interval 0.76 to 1.14.
Homologues: Orthologues: chimpanzee PLA2G5 (99% identical), macaque PLA2G5 (90% identical), dog PLA2G5 (82% identical), pig PLA2G5 (80% identical), mouse Pla2g5 (78% identical), rat Pla2g5 (78% identical), guinea pig PLA2G5 (70% identical), tropical clawed frog pla2g2e (32% identical), Caenorhabditis elegans C03H5.4 (29% identical), Caenorhabditis elegans C07E3.9 (28% identical). Paralogues in human: PLA2G2A (45% identical), PLA2G2E (43% identical), PLA2G2D (43% identical), PLA2G2F (40% identical), PLA2G10 (37% identical), PLA2G1B (33% identical), PLA2G2C (29% identical), OC90 (28% identical).
Diseases named in the same sentence as PLA2G5 in open-access papers:
PLA2G5 is named in the same sentence as 43 diseases in open-access papers, as found by Europe PMC text mining. Sharing a sentence is not in itself a finding about the gene and the disease. The quoted sentences say what the papers report.
Obesity (5 papers, 2016 to 2022). Accumulation of substantial excess body fat. "Notably, in humans, Pla2g5 gene polymorphisms correlate with the LDL levels in subjects with type 2 diabetes or obesity." (PMID 29259680, 2016). "Given the increased incidence of metabolic disorders resulting from the genetic ablation of Th2 or M2 inducers (e.g., Il4, Il13, Il33, Stat6, or Pparg), the decreased whole-body Th2/M2 status resulting from Pla2g5 deficiency may also contribute to the exacerbation of obesity-associated inflammation." (PMID 29259680, 2016). "PLA2G5 protects against diet-induced obesity and insulin resistance with an additional function in the translation of macrophages from adipose tissue from the M1 to M2 state." (PMID 36386829, 2022). "In addition, PLA2G5 knockout mice have hyperlipidaemia, increased obesity, hepatic steatosis, lower insulin sensitivity, greater infiltration of M1 macrophages, and a higher expression of proinflammatory cytokines." (PMID 36386829, 2022). "The PLA2 family members, which were identified in human placental tissue and appear to be involved in the aberrant lipid metabolism of pregnancies complicated by preeclampsia (PE) or obesity, are PLA2 group IIA (PLA2G2A) and PLA2 group V (PLA2G5)." (PMID 35743292, 2022). "And it was reported that members of the phospholipase A2 (PLA2) family of enzymes, such as PLA2G1B, PLA2G5, and PLA2G2E, can serve a distinct role in generating active lipid metabolites, which can promote inflammatory metabolic diseases including obesity." (PMID 29132311, 2017). "Notably, when fed a high-fat diet (HFD), Pla2g5−/− mice display hyperlipidemia with higher plasma levels of LDL, increased obesity and hepatic steatosis, and lower insulin sensitivity." (PMID 29259680, 2016). "Apart from the crucial role of adipocyte- rather than macrophage-derived sPLA2-V in obesity, the Pla2g5 expression in macrophages is markedly induced by the M2-skewing Th2 cytokines IL-4 and IL-13 and the Pla2g5 ablation decreases the Th2-mediated immune responses." (PMID 29259680, 2016).
glioma (4 papers, 2021 to 2023). A benign or malignant brain and spinal cord tumor that arises from glial cells (astrocytes, oligodendrocytes, ependymal cells). "PLA2G5 (phospholipase A2 group V) was reported to be associated with epithelial-mesenchymal transition and the isocitrate dehydrogenase one mutation status in gliomas." (PMID 34566519, 2021). "PLA2G5 is significant for tumorigenesis in low-grade gliomas and GBM." (PMID 36765904, 2023).
atherosclerosis (3 papers, 2011 to 2021). A disease characterized by the build-up of fatty material and calcium deposition in the arterial wall resulting in partial or complete occlusion of the arterial lumen. "sPLA2-V can also potently hydrolyze phospholipids in low-density (LDL) and high-density (HDL) lipoprotein particles, and LDL receptor-deficient mice transplanted with Pla2g5−/− bone marrow cells are partially protected from atherosclerosis development." (PMID 21673902, 2011). "Studies using Pla2g5−/− mice have also revealed unique functions of sPLA2-V in inflammation, host defense, and atherosclerosis." (PMID 21673902, 2011).
idiopathic pulmonary fibrosis (3 papers, 2019 to 2025). Idiopathic pulmonary fibrosis (IPF) is a nonneoplastic pulmonary disease that is characterized by the formation of scar tissue within the lungs in the absence of any known cause. "Interestingly, all these six dominant isoforms were found to be present only in structural cells like fibroblasts (PLA2G2A and PLA2G5), mesothelial cells (PLA2G2A) and epithelial cells (PLA2G1B, PLA2G3, PLA2G10 and PLA2G12A) that are key players in lung fibrosis." (PMID 37048117, 2023).
colon adenocarcinoma (2 papers, 2008 to 2022). "Interestingly, we observed marked alterations in the expression levels of PLA2G2D, PLA2G5 and PLA2G3 in colon adenocarcinomas." (PMID 18212756, 2008).
colorectal cancer (2 papers, 2008 to 2024). A primary or metastatic malignant neoplasm that affects the colon or rectum. "Interestingly, the PLA2G2A, PLA2G2C, PLA2G2D, PLA2G2E, PLA2G2F and PLA2G5 genes reside within the same region of human chromosome 1 at p35–36.1, a region frequently altered in colorectal cancer." (PMID 18212756, 2008). "Consistently, SELENOI was significantly upregulated in human colorectal cancer tissues, while PLA2G2A, PLA2G5, and ALOX15 were significantly downregulated." (PMID 38757622, 2024).
Coronary Artery Disease (2 papers, 2014 to 2023). "For instance, elevated plasma sPLA2-IIA (encoded by the PLA2G5 gene) predicts coronary heart disease risk and is involved in inflammation." (PMID 37239897, 2023). "The aim of the present study was to analyze if PLA2G5 gene polymorphisms are associated with premature coronary artery disease (CAD) in a case-control association study (GEA or genetics of atherosclerotic disease)." (PMID 24959594, 2014).
COVID-19 (2 papers, 2023 to 2026). A disease caused by infection with severe acute respiratory syndrome coronavirus 2. "In humans with bacterial or fungal sepsis or severe COVID-19, plasma PLA2G5 levels were elevated and predicted disease severity." (PMID 42065236, 2026). "In fact, we observed that GC therapy elevated cPLA2 enzyme-corresponding genes (PLA2G4A and PLA2G5) in COVID-19 patient blood cells." (PMID 36851787, 2023). "The gene expression of PLA2 isoforms, PLA2G4A and PLA2G5, were upregulated, while PLA2G6 and PLA2G7 were downregulated in COVID-19 patients using GCs, compared to non-treated COVID-19 patients and controls." (PMID 36851787, 2023).
diabetes (2 papers, 2012 to 2021). "For example, high expression of Pla2g5 and/or Prl5a1, as well as low expression of Ankrd2 and/or Pappa2, indicates exposure to diabetes, while low expression of Kcnk2 and/or Mmp13 indicates exposure to breeder diet." (PMID 22701643, 2012).
pneumonia (2 papers, 2021 to 2023). An acute, acute and chronic, or chronic inflammation focally or diffusely affecting the lung parenchyma, caused by an infection in one or both of the lungs (by bacteria, viruses, fungi, or mycoplasma.). "In brief, QKL treatment probably reduced the gene (Pla2g2a, Pla2g5, and Alox12e) expression and AA levels to alleviate pneumonia." (PMID 37362920, 2023).
Sepsis (2 papers, 2026). Sepsis is defined as life-threatening organ dysfunction caused by a dysregulated host response to infection. "Treatment with a PLA2G5 antibody during sepsis was associated with increased splenic red pulp macrophages and improved iron homeostasis, linking PLA2G5 to red blood cell homeostasis during sepsis." (PMID 42065235, 2026). "The genetic deletion of Pla2g5 and treatment with a PLA2G5 antibody were both associated with protection from lethal sepsis." (PMID 42065235, 2026). "We conclude that sepsis corrupts PLA2G5 into becoming an intravascular hemolytic factor which is toxic for host red blood cells." (PMID 42065235, 2026). "In humans with sepsis due to bacterial, fungal, or viral infections, the serum level of PLA2G5 was elevated and predictive of disease severity and mortality." (PMID 42065235, 2026). "Here, by measuring organism-wide changes in gene expression, we discovered that the secreted phospholipase PLA2G5 is induced in colon cell types during sepsis." (PMID 42065235, 2026). "In this issue, Takahama and colleagues identified phospholipase A2 Group V (PLA2G5) as a contributor to sepsis lethality in mouse models of endotoxemia and sepsis." (PMID 42065236, 2026). "This discovery highlights the contribution of hemolysis to sepsis, suggesting that PLA2G5 inhibitors, hemoglobin, or heme antagonists could represent valuable therapeutic tools." (PMID 42065236, 2026).
type 2 diabetes (2 papers, 2014 to 2020). "This phenotype is reminiscent of clinical evidence that a PLA2G5 polymorphism is associated with plasma LDL levels in patients with type 2 diabetes and that the levels of PLA2G5 mRNA expression in WAT are inversely correlated with plasma LDL levels in obese subjects." (PMID 33086624, 2020).
acute coronary syndrome (1 paper, 2014). Signs and symptoms related to acute ischemia of the myocardium secondary to coronary artery disease. "In the same way, the PLA2G5 deficiency does not affect the atherosclerotic lesion development in mice and pan-sPLA2 inhibitor varespladib did not reduce the risk of cardiovascular events after acute coronary syndrome." (PMID 24959594, 2014).
allergic bronchopulmonary aspergillosis (1 paper, 2025). Allergic bronchopulmonary aspergillosis (ABPA) is a rare immunologic pulmonary disorder caused by hypersensitivity to Aspergillus fumigatus, clinically manifesting with poorly controlled asthma and recurrent pulmonary infiltrates. "Studies have found high expression of Pla2g4c, Pla2g2c, Pla2g2d, and Pla2g5 in a mouse model of ABPA (allergic bronchopulmonary aspergillosis)." (PMID 40278587, 2025).
endometriosis (1 paper, 2021). The growth of functional endometrial tissue in anatomic sites outside the uterine body. "Identified DEGs in four endometriosis datasets, but PLA2G5 had the different regulatory." (PMID 34409913, 2021).
Hypertension (1 paper, 2014). The presence of chronic increased pressure in the systemic arterial system. "This agrees with our study, in which an association of the PLA2G5 haplotype with hypertension was detected." (PMID 24959594, 2014). "In summary, our study demonstrates the association of the PLA2G5 rs11573191 polymorphism with premature CAD and with hypertension in this group of patients." (PMID 24959594, 2014). "Considering that this is the first work to report an association of the PLA2G5 polymorphisms with premature CAD and hypertension, replication in another group of patients is necessary." (PMID 24959594, 2014). "PLA2G5 polymorphisms were in linkage disequilibrium and the CGA haplotype was associated with increased risk of premature CAD (OR = 1.49, P = 0.0023) and with hypertension in these patients (OR = 1.75, P = 0.0072)." (PMID 24959594, 2014).
melanoma (1 paper, 2023). A malignant, usually aggressive tumor composed of atypical, neoplastic melanocytes. "To predict the prognosis of melanoma patients, we calculated the risk score of each patient based on the expression and corresponding lambda value of seven genes (PLA2G2D, FUT8, PLA2G4E, PLA2G5, PLA2G1B, B3GNT2, and ST3GAL5)." (PMID 37205993, 2023).
respiratory failure (1 paper, 2011). The significant impairment of gas exchange within the lungs resulting in hypoxia, hypercarbia, or both, to the extent that organ tissue perfusion is severely compromised. "We found that Pla2g5-Tg mice died in the neonatal period (within 8 h after birth) due to respiratory failure." (PMID 21673902, 2011).
retinal diseases (1 paper, 2017). "For example, the TNFAIP3 gene is highly expressed in human retina from the same ATSS as in mouse, the same is true for PLA2G5, a gene from the RetNet list for mapped loci and genes causing retinal diseases that has been implicated in recessive benign fleck retina." (PMID 28640837, 2017).
tumor (5 papers, 2008 to 2025). "Interestingly, this correlation analysis showed that mainly in the ICD clinical settings tumoural CALR levels positively correlated with the tumoural levels of phagocytosis-associated genes (especially PLA2G5, PLD1, RAB5A, VAMP7, STAB2)." (PMID 26314964, 2015). "Key genes such as LGALS1, PLA2G5, and FABP5 were upregulated in high-risk patients and enriched in M2-like tumor-associated macrophages." (PMID 41164132, 2025). "Similar data were obtained for samples from the right colon, with a 22-fold increased expression in tumour vs normal mucosa for PLA2G3, and 10- and 44-fold reduced expression for PLA2G2D and PLA2G5, respectively." (PMID 18212756, 2008). "The qRT-PCR results, based on 15 clinical GBM and paired non-tumor brain tissue samples, showed that the mRNA levels of ALOX5AP, LGALS1, and PLA2G5 were significantly higher in GBM tumor tissues compared to non-tumor brain tissues (all p < 0.05)." (PMID 41164132, 2025).
cancer (4 papers, 2022 to 2025). A tumor composed of atypical neoplastic, often pleomorphic cells that invade other tissues. "Compared with normal breast tissues, PIGR, GPLD1, PLA2G5 and CORO1A were down-regulated in cancer tissues, while EIF4EBP1 and LPCAT1 were significantly up-regulated." (PMID 41450825, 2025). "Another very prominent pathway in cancer is ERK/MAPK signaling (p = 3.47 × 10−2; ESR1, FYN, ITGA3, PIK3R3, PLA2G4A, PLA2G5, RPS6KA5), which is the core of the signaling network involved in regulating cell growth, development, and division and a target of many cancer therapeutics." (PMID 35106465, 2022).
cardiovascular disease (2 papers, 2023). "Another secretory PLA2 highly associated with cardiovascular disease is sPLA2-V, encoded by PLA2G5." (PMID 36835616, 2023). "The intronic variant rs525380 influences the expression of PLA2G5 and the A allele is related to gene upregulation; however, it does not seem to be casually related to the pathogenesis of cardiovascular diseases." (PMID 36835616, 2023).
adenocarcinoma (1 paper, 2008). A common cancer characterized by the presence of malignant glandular cells. "A marked decrease in the expression level of PLA2G2D and PLA2G5 was observed in both left- and right-sided adenocarcinomas." (PMID 18212756, 2008). "In adenocarcinomas from left and right colon, the expression of PLA2G3 was increased by up to 40-fold, while that of PLA2G2D and PLA2G5 was decreased by up to 23- and 14-fold." (PMID 18212756, 2008).
retinopathy (1 paper, 2023). "Third, how are the autofluorescent flecks of PLA2G5 retinopathy reconciled with the infrequent autofluorescence of AMD SDD?" (PMID 38186747, 2023).
PLA2G5 also shares sentences with these, for which no sentence is quoted: Insulin resistance (2 papers); acute lung injury (1); acute respiratory distress syndrome (1); alcoholic gastritis (1); Allergy (1); asthma (1); bacterial infection (1); chronic thromboembolic pulmonary hypertension (1); colon cancer (1); endotoxemia (1); ependymoma (1); gout (1); Hepatic steatosis (1); Hyperglycemia (1); hyperlipidaemia (1); infection (1); mood disorder (1); respiratory diseases (1); viral infections (1).